AVP (arginine vasopressin)
Diseases named in the same sentence as AVP in open-access papers (continued):
Sharing a sentence is not in itself a finding about the gene and the disease.
autism (36 papers, 2009 to 2025). Persistent deficits in social interaction and communication and interaction as well as a markedly restricted repertoire of activity and interest as well as repetitive patterns of behavior. "AVP concentrations in the CSF were found to be lower in children with autism, and AVP levels were associated with the severity of symptoms." (PMID 35207180, 2022). "It is worth noting that OT and AVP have been implicated in autism and autism spectrum disorders, with a sex-related pattern." (PMID 19165396, 2009). "In humans, genes encoding oxytocin and arginine vasopressin pathways have been associated with individual variation in social recognition, social attachment phenotypes, parental behavior, and psychiatric phenotypes such as autism." (PMID 33800722, 2021). "Furthermore, AVP has been implicated in male vulnerability to autism and higher mortality rates in premature male infants." (PMID 30109601, 2019). "Similarly, in girls with autism, plasma levels of AVP have been linked to the intensity of repetitive behaviors." (PMID 25705203, 2015). "Further, autism has been linked to a mutation in V1a receptor genes raising the possibility that AVP may play a role in the impaired social behavior in autism." (PMID 25853137, 2015). "Furthermore, disorders of social behavior such as autism and schizophrenia that have been linked with AVP also have been linked with dysfunctions in sensory processing." (PMID 25705203, 2015). "Based on prior evidence suggesting a role for AVP in human and animal social cognition, and prior reports of genetic association between variants in vasopressin-related genes and autism, we hypothesized that variants in AVPR1A would be associated with autism in our Irish autism sample." (PMID 21453499, 2011). "Indeed, the AVP gene encodes the ligand for the AVP receptor 1a (AVPR1a) and polymorphisms in this last gene have been shown to be in linkage and in linkage disequilibrium with autism." (PMID 20885821, 2010). "The study found that intranasal administration of AVP, compared to a placebo, significantly enhanced the social abilities of children with autism." (PMID 39295107, 2024). "Clinical studies have also found that intranasal administration of AVP can improve social impairments in children with autism." (PMID 39295107, 2024). "The social preference index in social preference test was significantly decreased in the VPA-induced autism model group compared with the control group (p < 0.01) and AVP group (p < 0.01)." (PMID 35401102, 2022). "Male offspring prenatally exposed to VPA were randomly assigned to two groups: the VPA-induced autism model group and the AVP group." (PMID 35401102, 2022). "The time in the side with stranger 1 were significantly lower in the VPA-induced autism model group than control (p < 0.01) and AVP group (p < 0.01)." (PMID 35401102, 2022). "It provides a mechanistic framework to understand how does arginine vasopressin improve autism social interaction disorder." (PMID 36239083, 2022). "Genes in clusters 1 and 8 presented a trend of increasing in the VPA-induced autism model group and decreasing in the AVP group." (PMID 35401102, 2022). "The intersection of the gene expression variation between down in the VPA-induced autism model group (con vs. mod) and up in AVP (mod vs. AVP) was analyzed by Evenn3." (PMID 35401102, 2022). "Third, the roles of the AVP system in neurodevelopmental disorders, especially autism and schizophrenia, are only beginning to be explored." (PMID 35586834, 2022). "Genes in cluster 1 presented a trend of decreasing in VPA‐induced autism model group and increasing in AVP group." (PMID 36239083, 2022). "The autism model was induced by intraperitoneally injected with VPA at embryonic day 12.5 and randomly assigned to two groups: the VPA‐induced autism model group and the AVP treatment group." (PMID 36239083, 2022).
autism (continued). "In one published autism trial, chronic intranasal arginine vasopressin (AVP) was found to positively impact social responsiveness in children with ASD." (PMID 35745751, 2022). "We have demonstrated that AVP can significantly improve social dysfunction in VPA‐induced rats with autism in previous studies." (PMID 36239083, 2022). "Genes in clusters 5 and 7 presented a trend of decreasing in the VPA-induced autism model group and increasing in the AVP group." (PMID 35401102, 2022). "Compared with the control group, the AVP level in the serum significantly decreased in the VPA-induced autism model group (p < 0.01)." (PMID 35401102, 2022). "To further explore the mechanisms of action of AVP, we compared the PFC transcriptome changes before and after AVP treatment in VPA‐induced autism rat model." (PMID 36239083, 2022). "The results suggest that the social interaction was impaired in the VPA-induced autism model group, and the impairment was significantly improved following AVP treatment." (PMID 35401102, 2022). "Genes in cluster 4 presented a trend of increasing in VPA‐induced autism model group and decreasing in AVP group." (PMID 36239083, 2022). "Dynamic expression patterns analysis also showed genes/gene sets of these biological processes tended to decrease in the VPA‐induced autism model group and increase after AVP treatment." (PMID 36239083, 2022). "How do these conceptualizations of loneliness, and autism, relate to theory and evidence for the contextual adaptive significance of AVP and OXT?" (PMID 35586834, 2022). "Promising clinical trials in recent years have reported the pro-social role of the AVP system in autism." (PMID 34769501, 2021). "The relationship of CSF levels of AVP to plasma levels is of interest in studies of autism, suicide and personality disorders and the two compartments seem to be separately regulated." (PMID 33472866, 2021). "We predict that the AGTR2 variants involved in the brain maturation and oxytocin-arginine-vasopressin (OXT-AVP) pathways, related to social behavior, will contribute to our understanding of the link between prematurity and autism paving a way to new therapies." (PMID 30109601, 2019). "Arginine vasopressin, especially in its inhaled form, seems to be safe and beneficial in improving social functioning, including in children with autism." (PMID 31331023, 2019). "AVP, especially in its inhaled form, seems to be safe and beneficial in improving social functioning including in children with autism." (PMID 31331023, 2019). "In humans, attempts have been made to link AVP with disorders that affect social behavior and involve sensory processing issues such as autism and schizophrenia [reviewed in Ref." (PMID 25705203, 2015). "This latter experiment indicated that ICV delivery of both OT and AVP reduced some of these autism-like difficulties via the AVPV1a receptor." (PMID 23508240, 2013). "The role of sex hormones on AVP is of interest in the context of autism considering that the ratio of affected males with autism compared to affected females is highly skewed (4:1)." (PMID 21453499, 2011). "Compared with the control group, the mRNA levels of synaptic development‐related genes SYN1, SYNPO, and axon development‐related genes Lingo‐1 were significantly increased in the VPA‐induced autism model group (p < 0.01) and improved after AVP treatment (p < 0.01)." (PMID 36239083, 2022). "When compared with the control group, the cumulative self-grooming time was significantly prolonged in the VPA-induced autism model group (p < 0.01), and the cumulative time was significantly shorter in the AVP treatment group (p < 0.01) when compared with the VPA-induced autism rats." (PMID 35401102, 2022). "Furthermore, the social preference index in social novelty test was significantly decreased in the VPA-induced autism model group compared with the control group and AVP group (p < 0.01)." (PMID 35401102, 2022).
autism (continued). "By contrast, trait-based loneliness is much more closely akin to autism, and should, by the hypothesis and evidence described here, involve alterations to the AVP and/or OXT systems that are maladaptive and present from birth or environmentally induced." (PMID 35586834, 2022). "Recent replicated studies showing low cerebrospinal AVP among individuals with autism indeed suggest a key role for this hormone in autism-related phenotypes, and longstanding reports of high AVP in acute schizophrenia or psychosis suggest unrecognized impacts in this disorder as well." (PMID 35586834, 2022). "The precise neuroendocrine effects of AVP and its receptors in autism etiology and traits thus remain unclear." (PMID 35586834, 2022). "Some studies have shown that arginine vasopressin (AVP) can significantly improve the social interaction disorder of autism, but the mechanism remains unclear." (PMID 35401102, 2022). "In addition, AVP modulation of LS is of high interest given the abnormal levels of AVP observed in patients with autism and schizophrenia." (PMID 35581296, 2022). "Six KEGG gene sets were found remarkable upregulated in VPA‐induced autism model group and downregulate in AVP treatment, such as neuroactive ligand–receptor interaction, vibrio cholerae infection, calcium signalling pathway, N‐glycan biosynthesis, proteasome and oocyte meiosis." (PMID 36239083, 2022). "Although AVP treatment significantly improved social interaction disorders in VPA-induced autism model rats, the mechanism remains unclear." (PMID 35401102, 2022). "In addition, the mRNA levels of brain development‐related genes CHD7 and oligodendrocyte development‐related genes Olig2 and MBP were significantly decreased in the VPA‐induced autism model group (p < 0.01), and improved after AVP treatment (p < 0.01)." (PMID 36239083, 2022). "By pathway enrichment analysis, we found that the neuroactive ligand–receptor interaction and Calcium signalling pathway had the same change trend with synaptic development which significantly increased in the VPA‐induced autism model and decreased after AVP treatment." (PMID 36239083, 2022). "Moreover, the AVP concentration in the CSF in neonates made it possible to predict a subsequent diagnosis of autism." (PMID 35207180, 2022). "However, in the past few years, several pharmaceutical companies have been developing and testing AVP alternatives for CNS disorders, such as migraine or autism (see the next section)." (PMID 34769501, 2021). "Plasma OT and AVP show sex-specific relationships to autism symptoms." (PMID 25221489, 2014). "Arginine vasopressin (AVP) has been hypothesized to play a role in aetiology of autism based on a demonstrated involvement in the regulation of social behaviours." (PMID 21453499, 2011). "The neuropeptide arginine vasopressin (AVP) has been hypothesized to play a role in the aetiology of autism based on a demonstrated involvement in social bonding and in the regulation of a variety of socially relevant behaviours in animal models." (PMID 21453499, 2011). "Clearly, AVP signaling pathway may be a promising therapeutic target for autism." (PMID 35401102, 2022). "By contrast, dysfunction of the AVP system is predicted to manifest as the inability to handle complex social situations and successfully integrate into groups, resulting in emotions like loneliness or psychological conditions such as autism that are characterized by social problems." (PMID 35586834, 2022). "Thus, impairments in the AVP/OXT systems might be associated with aberrant brain morphology and function in autism." (PMID 28258508, 2017). "Blood AVP concentrations likewise were not examined in ASD discordant siblings, despite the possibility that AVP concentrations could be related to the “broad autism phenotype”, in which relatives of individuals with ASD show subclinical impairments in social and biological functioning." (PMID 26200852, 2015).
autism (continued). "Indeed, converging evidence suggests that AVP may be involved in social disorders such as autism as well as in normal aspects of human social behavior." (PMID 22697211, 2012). "In summary, our results have revealed AVP can significantly improve synaptic and axon dysplasia and promote oligodendrocyte development in the prefrontal cortex in VPA‐induced autism models by regulating multiple signalling pathways." (PMID 36239083, 2022). "Today, the AVP has already entered phase II clinical trials (NCT01962870, NCT03204786) for the treatment of autism." (PMID 35401102, 2022). "Our previous studies have also demonstrated that AVP can significantly improve social interaction disorders and stereotypical behaviours in rats with VPA‐induced autism model." (PMID 36239083, 2022). "In addition, Carson and colleagues recently found that plasma AVP concentrations can be used to predict AVP levels in the cerebrospinal fluid of children, and might serve as a biomarker for social function in children with autism." (PMID 28258508, 2017). "Blood samples for sex hormone analysis were collected from 108 mothers (61 in autism, 47 in control group), of which 86 samples (40 in autism, 26 in control group) were tested for OXT and AVP concentrations." (PMID 24086383, 2013). "To explore the potential for AVP as a treatment for autism and to further explore their mechanisms of action, we compared the amygdala transcriptome changes before and after AVP treatment in VPA-induced autism rat model." (PMID 35401102, 2022). "Our results confirmed that AVP could significantly improve synaptic and axon dysplasia and promote oligodendrocyte development in the prefrontal cortex in VPA‐induced autism models by regulating multiple signalling pathways." (PMID 36239083, 2022). "The overlapping distributions of the two neuropeptides, as revealed by other studies in autistic children, remind us that multiple factors contribute to the development of autism and a simple deficit of OXT or AVP is far from enough to interpret the etiology of this highly heterogeneous illness." (PMID 24086383, 2013). "Furthermore, some neurodevelopment-related BPs such as glial cell proliferation, glial cell migration, neural tube development, and so on were not changed in the VPA-induced autism model group but remarkably upregulated after AVP treatment." (PMID 35401102, 2022). "Furthermore, some glial cell development‐related BP such as oligodendrocyte differentiation, oligodendrocyte development, glial cell differentiation, glial cell development, gliogenesis and so on were not change in VPA‐induced autism model group but remarkable up regulated after AVP treatment." (PMID 36239083, 2022). "Collectively, these results demonstrate that AVP can significantly improve the social interaction disorder of VPA-induced autism model, and AVP may target behavioral symptoms in autism by modulating the vasopressin pathways, rather than primary disease mechanisms." (PMID 35401102, 2022). "AVP can significantly improve the social interaction disorder of VPA-induced autism model, and AVP may target behavioral symptoms in autism by modulating the vasopressin pathways, rather than primary disease mechanisms." (PMID 35401102, 2022). "Specifically, whereas OT (but not AVP) normalizes deficits in OT and CD38 knockout mice, both OT and AVP normalize defects in OT-receptor knockout mice, which demonstrate an autism-like profile (deficits in social behavior, seizures)." (PMID 23508240, 2013).
Obesity (31 papers, 2014 to 2025). Accumulation of substantial excess body fat. "The interactions between AVP and insulin are significantly affected in hypertension, cardiac failure, obesity, insulin deficiency, and insulin resistance." (PMID 39769071, 2024). "For example, AVP resistance, a chronic elevation in plasma AVP levels and decreased responsiveness of AVP receptors, is a leading factor in the development of obesity caused by increased food intake and impaired glucose metabolism." (PMID 33796071, 2021). "In mice, the induction of a missense mutation in the Otp gene causes acute onset obesity and increased anxiety, phenotypes that have similarly been shown to be modulated by AVP and OT." (PMID 33519393, 2020). "Bbs10−/− mice developed obesity, retinal degeneration, structural defects in the glomeruli, polyuria associated with high circulating arginine vasopressin (AVP) concentrations, and vacuolated, yet ciliated, renal epithelial cells." (PMID 26273430, 2015). "Obesity, NE dosage < 0.30 mcg/kg/min, and hyperlactatemia were negatively associated with AVP responsiveness, while NE infusion rate and duration, BMI and arterial pH at AVP initiation were associated to shock duration." (PMID 40299108, 2025). "attributed the elevated serum Copeptin level in overweight children and adolescents to the role played by Copeptin, as one of the mediators associated with chronic stress like obesity and metabolic syndrome, i.e. activation of the hypothalamic-pituitary-adrenal axis by AVP." (PMID 38402172, 2024). "arginine vasopressin (AVP) is associated with the development of obesity, but may be responsible for the improvement of insulin resistance." (PMID 30678306, 2019). "Obesity, NE infusion rate < 0.30 mcg/kg/min, and hyperlactatemia were negatively associated with AVP responsiveness, and high NE infusion rate and longer duration at AVP initiation alongside higher BMI and lower baseline arterial pH were associated with prolonged shock duration in shock survivors." (PMID 40299108, 2025). "Obesity and hyperlactatemia was negatively associated with AVP-response (adjusted Odds Ratio [aOR] 0.30, 95%CI 0.14–0.65 and aOR 0.86, 95%CI 0.75–0.99, respectively), while a NE infusion rate ≥ 0.30 μg/kg/min showed positive odds of AVP response (aOR 2.33, 95%CI 1.06–5.14)." (PMID 40299108, 2025). "Studies on overweight/obese women have shown that that obesity is associated with higher ACTH and cortisol responses to AVP tests than those of women with normal body weight, the control, which suggests that obesity may cause the disarrangement of interactions of vasopressin with the HPA." (PMID 39000501, 2024). "V1aR knockout models, which lack the receptor on which AVP exerts its vasoconstrictive abilities, are prone to obesity." (PMID 40299108, 2025). "Elevated AVP levels are seen in various metabolic conditions, such as insulin resistance, metabolic syndrome, type 2 diabetes (T2D) and obesity, further highlighting its potential role as a metabolic regulator." (PMID 40428796, 2025). "For instance, certain polymorphisms, such as AVP rs3729965 and AGTR2 C4599A, exhibit obesity-dependent risks." (PMID 39408215, 2024). "The mutant mice responded with elevation of plasma AVP levels and developed overt obesity when they were maintained on a high-caloric intake, while the same diet was not effective in wild-type mice." (PMID 38279313, 2024). "CREB mediates the effects of canonical MC4R signalling through the Gαs–cAMP–PKA cascade, and mice with genetic deletion of Creb1 in Sim1 neurons develop obesity, impaired thermogenesis, and reduced AVP expression." (PMID 36175420, 2022). "As there is now considerable evidence that AVP plays a crucial role in feeding behavior and energy balance, it has become a promising therapeutic target for treating obesity or other obesity-related metabolic disorders." (PMID 33905792, 2021). "AVP (ENSP00000369647) as the following predicted gene has been confirmed to be abnormally hyperactivity in obesity." (PMID 29258237, 2017).